HSPB2-C11orf52 (HSPB2-C11orf52 readthrough (NMD candidate))
Synonyms: C11orf52
Gene: Protein-coding gene on chromosome 11 (111,912,736 to 111,926,871, forward strand). Ensembl gene ENSG00000254445.
Genetic constraint (gnomAD): Missense variants: 242 observed, 244.39 expected, observed/expected ratio (o/e) 0.99, 90% interval 0.89 to 1.1. Synonymous variants: 110 observed, 107.28 expected, observed/expected ratio (o/e) 1.03, 90% interval 0.88 to 1.2.